KIF1A (kinesin family member 1A)
Description:
Kinesin motor with a plus-end-directed microtubule motor activity (By similarity). It is required for anterograde axonal transport of synaptic vesicle precursors. Also required for neuronal dense core vesicles (DCVs) transport to the dendritic spines and axons. The interaction calcium-dependent with CALM1 increases vesicle motility and interaction with the scaffolding proteins PPFIA2 and TANC2 recruits DCVs to synaptic sites.
Synonyms: ATSV; C2orf20; UNC104; HSN2C; MRD9; NESCAVS; SPG30; SPG30A; SPG30B
Tractability: Small molecule: a structure with a bound ligand is known. Antibody: UniProt places it where antibodies can reach, with medium confidence. PROTAC: ubiquitination databases record sites on it; its protein half-life has been measured.
Target class: Other cytosolic protein
Gene: Protein-coding gene on chromosome 2 (240,713,761 to 240,824,320, reverse strand). Ensembl gene ENSG00000130294.
Subcellular location: Cytoplasm, cytoskeleton; Cell projection, neuron projection; Cell projection, axon; Cytoplasm, perinuclear region; Synapse; Cytoplasmic vesicle, secretory vesicle, neuronal dense core vesicle membrane
Subcellular location (Human Protein Atlas): Centriolar satellite; Cytosol
Pathways (Reactome):
Hemostasis: Kinesins
Vesicle-mediated transport: COPI-dependent Golgi-to-ER retrograde traffic
Gene Ontology:
Molecular function: identical protein binding; protein binding; cytoskeletal motor activity; plus-end-directed microtubule motor activity; ATP binding; microtubule binding; microtubule motor activity
Biological process: anterograde axonal transport; anterograde neuronal dense core vesicle transport; dense core granule cytoskeletal transport; regulation of dendritic spine development; regulation of dendritic spine morphogenesis; retrograde neuronal dense core vesicle transport; vesicle-mediated transport; microtubule-based movement; transport along microtubule
Cellular component: axon; dendrite; kinesin complex; neuronal dense core vesicle; synapse; axon cytoplasm; cytoskeleton; neuron projection; neuronal dense core vesicle membrane; perinuclear region of cytoplasm
Genetic constraint (gnomAD): Loss-of-function variants: 43 observed, 182.41 expected, observed/expected ratio (o/e) 0.24, 90% interval 0.18 to 0.3. The upper end of that interval is the gene's LOEUF score, 0.3, which puts it in group 1 of 6, group 1 being the genes least tolerant of losing a copy. Missense variants: 1,649 observed, 2,311.9 expected, observed/expected ratio (o/e) 0.71, 90% interval 0.68 to 0.74. Synonymous variants: 981 observed, 949.38 expected, observed/expected ratio (o/e) 1.03, 90% interval 0.98 to 1.09.
Gene-disease validity (ClinGen):
ClinGen rates the evidence that KIF1A causes each of these diseases.
syndromic intellectual disability (autosomal dominant): Definitive. A intellectual disability that is part of a larger syndrome.
Homologues: Orthologues: macaque KIF1A (99% identical), chimpanzee KIF1A (98% identical), dog KIF1A (98% identical), rat Kif1a (97% identical), mouse Kif1a (97% identical), guinea pig KIF1A (97% identical), pig KIF1A (97% identical), tropical clawed frog kif1a (81% identical), zebrafish kif1aa (80% identical). Paralogues in human: KIF1B (71% identical), KIF1C (33% identical), KIF13A (28% identical), KIF13B (28% identical), KIF16B (22% identical), KIF14 (21% identical), KIF21B (15% identical), KIF21A (15% identical), CENPE (14% identical), KIF17 (13% identical), KIF7 (13% identical), KIF4A (13% identical), and 29 more.
Diseases named in the same sentence as KIF1A in open-access papers:
KIF1A is named in the same sentence as 134 diseases in open-access papers, as found by Europe PMC text mining. Sharing a sentence is not in itself a finding about the gene and the disease. The quoted sentences say what the papers report.
Spastic paraplegia (22 papers, 2016 to 2026). Complete loss of the ability to move the lower limbs accompanied by spasticity of the lower limbs. "KIF1A is typically associated with spastic paraplegia, but our patients presented with isolated upper body dystonia (cranial, cervical, or upper limbs), with two patients exhibiting tremor and one muscle atrophy at the shoulders." (PMID 40533913, 2025). "The mutations related to ALS in our study were primarily located in the cargo-binding region at the C-terminal, as opposed to the mutations of motor domain at the N-terminal of KIF1A which were linked to hereditary peripheral neuropathy and spastic paraplegia." (PMID 39076207, 2024). "Another study reports that there is a link between the KIF1A mutations and autism and is normally characterized by other neurological conditions like sensory disturbance, hyperactivity, spastic paraplegia, and epilepsy." (PMID 37259299, 2023). "These types of spastic paraplegias are caused due to variations in the KIF1A gene and are referred to as an autosomal dominant type of Spastic Paraplegia (SPG30)." (PMID 37259299, 2023). "With the clinical data of the Polish cohort presented here, we can support the importance of KIF1A variants in the development of spastic paraplegia." (PMID 37239332, 2023). "Patients with de novo KIF1A-related variants have shown a complex phenotype, including developmental delay, ataxia, spastic paraplegia, and neuropathy, with onset in the first year of life." (PMID 35326432, 2022). "As an example, biallelic mutations in KIF1A cause spastic paraplegia, distal wasting, peripheral neuropathy and mild cerebellar signs (AR SPG30)." (PMID 33646413, 2021). "Mutations in KIF1A have been previously associated with disorders like spastic paraplegia 30 and hereditary neuropathy." (PMID 32758128, 2020). "Here, we describe 20 KIF1A variants in 24 patients from a clinical exome sequencing cohort of 347 individuals with a mostly ‘pure’ spastic paraplegia." (PMID 31488895, 2020). "In adults, Kif1A has been shown to be dysregulated following myocardial infarction and a Kif1A motor domain mutation has been associated with spastic paraplegia." (PMID 32498427, 2020). "In the present study, we identified a novel p.T258M mutation in KIF1A affecting mother and three children with spastic paraplegia that is inherited in a type of autosomal dominant manner." (PMID 28970574, 2017). "Both families with KIF1A variants presented with a childhood onset, slowly progressive spastic paraplegia." (PMID 28362824, 2017). "Here, the KIF1A gene has been associated with hereditary sensory and autonomic neuropathy type II and in autosomal recessive spastic paraparesis as well as spastic paraplegia." (PMID 27087860, 2016). "The significance of rehabilitation was suggested in pediatric patients with KIF1A mutations manifesting as spastic paraplegia phenotypes, for whom a deterioration in mobility likely occurred due to progressive spasticity, muscle weakness, and the secondary development of severe contractures." (PMID 36227410, 2023). "Kif1a is associated with non-syndromic intellectual disability and spastic paraplegia." (PMID 34021263, 2021). "Therefore, this novel heterozygous p.T258M mutation with autosomal dominant inheritance is meaningful in that it expands the phenotypic spectrum of KIF1A variants to include intellectual disability and spastic paraplegia." (PMID 28970574, 2017). "Genetic analysis identified a heterozygous c.31C>T (p.Arg11Trp) pathogenic variant in the KIF1A gene, consistent with NESCAV syndrome and spastic paraplegia." (PMID 41466769, 2026). "KIF1A and SHANK3 are enriched in neural tissues and are associated with neurodevelopmental disorders such as autism, epilepsy, or spastic paraplegia." (PMID 38370698, 2024).
Spastic paraplegia (continued). "AD SPG30 caused by various heterozygous KIF1A mutations is one of the most common HSP in Russian population: 10 SPG30 families amounted for 8.4% from the total 118 cases, that have been molecularly diagnosed by MPS panel -‘spastic paraplegias’." (PMID 32746806, 2020).
hereditary spastic paraplegia (19 papers, 2016 to 2025). Hereditary spastic paraplegias (HSP) comprise a genetically and clinically heterogeneous group of neurodegenerative disorders characterized by progressive spasticity and hyperreflexia of the lower limbs. "Initially, biallelic KIF1A variants were described with the phenotype of hereditary spastic paraplegia (SPG30) and hereditary sensory and autonomic neuropathy (HSAN2C)." (PMID 41585230, 2025). "Initially, biallelic pathogenic mutations in KIF1A were linked to two phenotypes: a recessive form of hereditary spastic paraplegia (HSP) called spastic paraplegia-30 (SPG30), and the hereditary sensory and autonomic neuropathy type II." (PMID 39125740, 2024). "Previous study suggest that KIF1A mutations that cause hereditary spastic paraplegia are loss-of-function mutations that decrease motility." (PMID 32174959, 2020). "A targeted NGS panel for hereditary spastic paraplegia and motoneuronal disorders disclosed the heterozygous candidate variant 241,715,312 NM_001244008.1 c.914C > T (NP_001230937.1 p.Pro305Leu) on KIF1A gene, arisen de novo." (PMID 31796088, 2019). "Homozygous mutations of KIF1A have been identified in a recessive subtype of hereditary spastic paraplegia (HSP), SPG30." (PMID 28970574, 2017). "KIF1A is responsible for the transport of membranous organelles and synaptic vesicles in neurons, and mutations in KIF1A have been associated with hereditary spastic paraplegia (HSP), hereditary sensory and autonomic neuropathy type 2 (HSANII), and intellectual disability." (PMID 32174959, 2020). "These diseases include hereditary spastic paraplegia, which has been linked to mutations in human KIF1A, and may also include ALS and Alzheimer’s disease, which have recently been linked to DLK." (PMID 28925357, 2017). "Variants of KIF1A have recently been associated with hereditary spastic paraplegia (HSP), hereditary sensory and autonomic neuropathy type 2 (HSANII), and intellectual disability." (PMID 32174959, 2020). "Mutations in the kinesin-3 family member KIF1A have been associated with hereditary spastic paraplegia (HSP), hereditary and sensory autonomic neuropathy type 2 (HSAN2) and non-syndromic intellectual disability (ID)." (PMID 27656128, 2016). "Variants in proteins involved in microtubule dynamics (SPAST), axonal maintenance (ATL1) and transport (KIF1A) are among the most common genetic etiologies both of cerebral palsy mimicries and of hereditary spastic paraplegia (HSP)." (PMID 40095113, 2025). "The first reported phenotypes of KIF1A mutation included pure hereditary spastic paraplegia (HSP)." (PMID 37239332, 2023). "Pathogenic variants in KIF1A were first associated with two neurodegenerative diseases in 2011: hereditary sensory and autonomic neuropathy (HSAN) type 2 and a form of AR hereditary spastic paraparesis (HSP)." (PMID 31796088, 2019). "Variants in the KIF1A gene have been described in patients with AR hereditary sensory and autonomic neuropathy type 2 (HSAN2, OMIM #614213) and subtype 30 of the hereditary spastic paraplegia (SPG30, OMIM #610357)." (PMID 30778698, 2019). "Of note, there are nine genes among these targets that when mutated are known causes for inherited peripheral neuropathies (IPN) and hereditary spastic paraplegia (HSP) (Inf2, Sox10, Wnk1, Med25, Fa2h, Bscl2, Slc12a6, Kif1a and Kif5a)." (PMID 28077174, 2017). "For KIF1A and KIF5A, mutations causing hereditary spastic paraplegia – associated with the dysfunction and degeneration of upper motor neurons – and amyotrophic lateral sclerosis alter the function of kinesins, motor proteins that shepherd vesicles up and down the microtubular routes along the axon." (PMID 34897416, 2021). "In addition, homozygous recessive mutations of KIF1A have been found in the hereditary sensory and autonomic neuropathy type 2 (HSANII) and in a recessive subtype of hereditary spastic paraplegia (HSP), SPG3018–21." (PMID 28970574, 2017).
neuropathy (15 papers, 2017 to 2025). A disorder affecting the nervous system that manifests with pain, tingling, numbness, and/or muscle weakness. "Determining the causality of KIF1A variants can be challenging in patients with adult-onset, slow progression, or neuropathy." (PMID 41585230, 2025). "It was shown both in Drosophila and humans that KIF1A mutation causes neuropathies, as it is also involved in synaptic vesicle transport." (PMID 34638976, 2021). "Previous studies have reported that several patients with mutations in KIF1A present recurrent seizures; however, these studies investigated only the correlation of neuropathy and brain malformation with mutations in KIF1A." (PMID 32174959, 2020). "Many point mutations in KIF1A have been identified to date, and these mutations have been associated with various neuropathies." (PMID 32174959, 2020). "Most KIF1A mutations causing the neuropathies are located within the conserved motor domain." (PMID 34843479, 2021). "The effects on autophagy in mutant KIF1A patients or cell/mouse models remains to be studied, but it is not inconceivable that impairment of autophagy due to disruption in ATG9 trafficking in KIF1A mutants is one of the pathomechanisms of neuropathy due to KIF1A mutations." (PMID 28553203, 2017). "A total of 129 pathogenic KIF1A variants (mostly missense variants, only 20 truncating) have been reported, mainly resulting in spastic paraplegia (pure or complicated), several variants with severe complex phenotype, and a few variants with mild neuropathy (according to HGMD Profess." (PMID 41585230, 2025). "Noteworthy, neuropathy is the most common complication of diabetes which has been shown to alter expression of KIF1A and can lead to hair follicle damage." (PMID 32758128, 2020). "Along the axonal MT in neurons, KIF1A transports synaptic vesicle precursors, which contain synaptic vesicle proteins, indispensable for synaptogenesis, while KIF1A mutants lead to severe neuronal degeneration, synaptic dysfunction, and neuropathies." (PMID 33557020, 2021). "Finally, heterozygous KIF1A knockout mice develop neuropathy at older age, indicating that KIF1A haploinsufficiency leads to a neurological phenotype." (PMID 31488895, 2020). "NESCAVS is caused by a mutation in the KIF1A gene, a gene also implicated in spastic paraplegia 30 (SPG30, MIM 610,357) and neuropathy, hereditary sensory, type IIC (HSN2C, MIM 614,213)." (PMID 36227410, 2023). "The phenotypic spectrum of KIF1A includes HSP, ataxia, neuropathy, developmental delay/intellectual disability, optic nerve atrophy, cerebellar atrophy, and hereditary sensory autonomic neuropathy." (PMID 37251230, 2023). "KIF1A-related disorders probably remain underdiagnosed because of the dominant relation with HSP and less known coincidence with a multisystem and progressive course with upper motor neuron dysfunction and extrapyramidal signs with neuropathy." (PMID 37239332, 2023).
Ataxia (14 papers, 2019 to 2025). Ataxia refers to impaired coordination of voluntary muscle movement. "We report a sporadic ataxia patient associated with a novel de novo missense mutation in KIF1A presenting with ataxia, intellectual disability, and mild foot deformity." (PMID 36227410, 2023). "We report a case in which a novel de novo KIF1A mutation was identified in a patient with ataxia, intellectual disability and mild foot deformity." (PMID 36227410, 2023). "Here, we report the use of WES to identify a novel KIF1A mutation in a patient with ataxia, intellectual disability, and mild foot deformity." (PMID 36227410, 2023). "This paradox has already been described in other patients with ataxia and mutations in KIF1A, ITPR1, and PMPCA but also in KCNC3, and CACNA1A genes." (PMID 36233161, 2022). "In conclusion, we describe here the effect on the KIF1A motor domain of a novel de novo missense variant associated with severe developmental delay, spastic paraparesis, motor sensory neuropathy, bilateral optic nerve atrophy, progressive cerebellar atrophy, epilepsy, ataxia, and hypotonia." (PMID 34121983, 2021). "Eleven patients showed very early-onset ataxia and CA with cortical hyperintensities caused by mutations in ITPR1, KIF1A, SPTBN2, PLA2G6, PMPCA, and PRDX3." (PMID 36233161, 2022). "A recent study showed that heterozygous mutations in KIF1A may result in two distinct phenotypes, a pure to complex HSP phenotype and a congenital or early-onset ataxia phenotype [28•]." (PMID 33646413, 2021). "The panel MPS (SPG and ataxia genes) in 48 HSP unrelated, mostly Dutch patients with earlier performed target DNA testing for several common SPG, detected 2 males (4.2%) with different heterozygous KIF1A mutations." (PMID 32746806, 2020). "Our case 30–10 with minimal spasticity, moderate ataxia, benign course with gradual improvement and non-severe congenital cataract that has not been reported previously may present a new variant of AD KIF1A-related phenotype." (PMID 32746806, 2020). "In 2006 autosomal recessive (AR) HSP with mild ataxia and sensory neuropathy was mapped to the locus 2q37.3 containing KIF1A and assigned to SPG30 (OMIM#610357)." (PMID 32746806, 2020).
Intellectual disability (14 papers, 2016 to 2026). "Various heterozygous de novo missense mutations on the KIF1A motor domain have been identified in patients who display intellectual disability along with atrophy and spastic paraplegia." (PMID 28970574, 2017). "Disease associated KIF1A mutations have been associated with motor and sensory dysfunctions as well as non-syndromic intellectual disability in humans." (PMID 28344334, 2017). "In conclusion, our data suggest that a novel heterozygous mutation (p.T258M) in KIF1A can induce HSP accompanying intellectual disability and this is the first case of familial complicated HSP transmitted in autosomal dominant inheritance." (PMID 28970574, 2017). "In terms of genotype-phenotype analysis of the five recurrent missense pathogenic variants, the three participants with p.(Arg11Gln) of KIF1A had a less severe phenotype in terms of visual impairment, intellectual disability, language disorder and social responsiveness impairment." (PMID 40379967, 2026). "Consequently, patients with genetic variants in the KIF1A gene can show varying degrees of intellectual disability, as well as neurodegeneration." (PMID 41209913, 2025). "However, our patients with the p.T258M mutation in KIF1A displayed phenotypes of intellectual disability with language delay, optic nerve hypoplasia, thinning of corpus callosum, periventricular white matter lesion, microcephaly, and epilepsy in addition to spasticity." (PMID 28970574, 2017). "The inheritance of complicated HSP with intellectual disability has not been reported as far, and our p.T258M KIF1A mutation is the first case of autosomal dominant inheritance in familial complicated HSP." (PMID 28970574, 2017).